SLC46A1 (solute carrier family 46 member 1)
Description:
Proton-coupled folate symporter that mediates folate absorption using an H(+) gradient as a driving force. Involved in the intestinal absorption of folates at the brush-border membrane of the proximal jejunum, and the transport from blood to cerebrospinal fluid across the choroid plexus. Functions at acidic pH via alternate outward- and inward-open conformation states. Protonation of residues in the outward open state primes the protein for transport. Binding of folate promotes breaking of salt bridge network and subsequent closure of the extracellular gate, leading to the inward-open state and release of protons and folate. Also able to transport antifolate drugs, such as methotrexate and pemetrexed, which are established treatments for cancer and autoimmune diseases. Involved in FOLR1-mediated endocytosis by serving as a route of export of folates from acidified endosomes. Also acts as a lower-affinity, pH-independent heme carrier protein and constitutes the main importer of heme in the intestine. Imports heme in the retina and retinal pigment epithelium, in neurons of the hippocampus, in hepatocytes and in the renal epithelial cells. Hence, participates in the trafficking of heme and increases intracellular iron content. [Isoform 2]: Inactive isoform which is not able to mediate proton-coupled folate transport.
Synonyms: HsPCFT; hPCFT; G21; HCP1; PCFT; MGC9564
Tractability: Small molecule: a high-quality ligand is known. Antibody: UniProt places it where antibodies can reach, with high confidence; its Gene Ontology location is reachable by antibodies, with high confidence; UniProt predicts a signal peptide or a membrane-spanning region; the Human Protein Atlas places it where antibodies can reach. PROTAC: ubiquitination databases record sites on it; a small molecule that binds it is known.
Target class: SLC superfamily of solute carriers; SLC46 family of folate transporters; Electrochemical transporter; Transporter
Chemical probes: CHEMBL605580
Gene: Protein-coding gene on chromosome 17 (28,394,642 to 28,407,197, reverse strand). Ensembl gene ENSG00000076351.
Subcellular location: Cell membrane; Apical cell membrane; Basolateral cell membrane; Endosome membrane; Cytoplasm
Subcellular location (Human Protein Atlas): Cytosol; Plasma membrane
Pathways (Reactome):
Cellular responses to stimuli: Heme signaling
Metabolism: Metabolism of folate and pterines
Transport of small molecules: Iron uptake and transport
Gene Ontology:
Molecular function: folic acid transmembrane transporter activity; folic acid:proton symporter activity; heme transmembrane transporter activity; proton transmembrane transporter activity; symporter activity; methotrexate transmembrane transporter activity; transmembrane transporter activity
Biological process: folate import across plasma membrane; folate transmembrane transport; folic acid transport; proton transmembrane transport; folic acid metabolic process; heme metabolic process; intestinal folate absorption; intracellular iron ion homeostasis; transmembrane transport; heme transport; methotrexate transport; tetrahydrofolate biosynthetic process
Cellular component: apical plasma membrane; basolateral plasma membrane; cell surface; cytosol; endosome; plasma membrane; cytoplasm; brush border membrane; endosome membrane; membrane
Genetic constraint (gnomAD): Loss-of-function variants: 17 observed, 29.49 expected, observed/expected ratio (o/e) 0.58, 90% interval 0.39 to 0.87. The upper end of that interval is the gene's LOEUF score, 0.87, which puts it in group 3 of 6, group 1 being the genes least tolerant of losing a copy. Missense variants: 517 observed, 574.77 expected, observed/expected ratio (o/e) 0.9, 90% interval 0.84 to 0.97. Synonymous variants: 240 observed, 257.08 expected, observed/expected ratio (o/e) 0.93, 90% interval 0.84 to 1.04.
Homologues: Orthologues: chimpanzee SLC46A1 (99% identical), dog SLC46A1 (88% identical), mouse Slc46a1 (87% identical), rat Slc46a1 (87% identical), rabbit SLC46A1 (87% identical), macaque SLC46A1 (86% identical), guinea pig SLC46A1 (85% identical), pig SLC46A1 (85% identical), tropical clawed frog slc46a1 (55% identical), zebrafish slc46a1 (54% identical). Paralogues in human: SLC46A3 (30% identical), SLC46A2 (22% identical).
Diseases named in the same sentence as SLC46A1 in open-access papers:
SLC46A1 is named in the same sentence as 28 diseases in open-access papers, as found by Europe PMC text mining. Sharing a sentence is not in itself a finding about the gene and the disease. The quoted sentences say what the papers report.
folate deficiency (12 papers, 2014 to 2026). A nutritional condition produced by a deficiency of FOLIC ACID in the diet. "For instance, severe folate deficiency in the brain can lead to germline mutations in SLC46A1 or the production of folate autoantibodies." (PMID 40792046, 2025). "HFM is a rare autosomal recessive disorder caused by mutations in SLC46A1, impairing both intestinal folate uptake and transport into the CNS, resulting in systemic and central folate deficiency." (PMID 40937236, 2025). "This study elucidates the molecular mechanism by which folate inhibits CRC progression through the "SLC46A1-epigenetic-transcriptional regulation" axis, providing mechanistic insights into folate deficiency-driven CRC progression and biomarkers for precision CRC intervention." (PMID 41620398, 2026). "Cerebral folate deficiency, caused by folate receptor autoantibodies or germline mutations in FOLR1 or SLC46A1, and insufficient folate intake around and during pregnancy have been associated with an increased risk of neural tube defects." (PMID 40792046, 2025). "Several previous studies have shown that folate deficiency results in a significant upregulation of folate transport genes such as SLC19A1/RFC-1 and SLC46A1/PCFT." (PMID 30269276, 2018). "Interestingly, heme inhibited folate uptake by downregulating SLC46A1 expression while folate did not affect heme uptake and SLC46A1 expression, suggesting that folate deficiency is caused by secondary hepatic heme uptake excess." (PMID 35832553, 2022).
colorectal cancer (3 papers, 2019 to 2026). A primary or metastatic malignant neoplasm that affects the colon or rectum. "In stage III colorectal cancer, high expression of SLC19A1 and SLC46A1 correlated with improved disease-free survival in patients receiving 5-FU/leucovorin." (PMID 41376620, 2025).
ovarian carcinoma (2 papers, 2021 to 2023). A malignant neoplasm originating from the surface ovarian epithelium. "The expression of CYBRD1, LRP2, TFRC, SLC22A17, HEPH, SLC39A14, and PCBP2 involved in iron import was associated with poor OS of ovarian cancer, whereas the expression of LCN2, CP, SLC46A1, STEAP3, and LTF in this process was associated with improved OS in ovarian cancer." (PMID 38186569, 2023).
B-cell acute lymphoblastic leukemia (1 paper, 2023). A neoplasm of lymphoblasts committed to the B-cell lineage, typically composed of small to medium-sized blast cells. "In addition, miR-5189, miR-595, and miR-6083 that might affect SLC46A1, SLC19A1, and SLCO1A2 MTX transport gene regulation and could affect MTX levels in patients with B-cell acute lymphoblastic leukemia." (PMID 37971595, 2023).
bladder cancer (1 paper, 2017). "In an intriguing example designed to exploit this phenomenon, investigators modified the structure of pemetrexed (PMX), a folate antimetabolite used in treatment of lung and bladder cancer, to favor uptake by the proton-coupled folate transporter (PCFT/ SLC46A1)." (PMID 28350329, 2017).
breast carcinoma (1 paper, 2021). "Consistent with our results, Hlavac and colleagues found that SLC46A1 variants are associated with ERBB2/HER2 status and disease-free survival in hormonally treated patients with breast carcinoma." (PMID 34055632, 2021).
cholangiocarcinoma (1 paper, 2021). A carcinoma that arises from the intrahepatic biliary tree (intrahepatic cholangiocarcinoma) or from the junction, or adjacent to the junction, of the right and left hepatic ducts (hilar cholangiocarcinoma). "The underlying mechanism by which SLC46A1 variants affect cholangiocarcinoma prognosis requires further research." (PMID 34055632, 2021). "In our prognostic model, we identified the key roles of SLC46A1 and IARS AS in predicting the OS in patients with cholangiocarcinoma." (PMID 34055632, 2021). "The CDK11A splicing factor and SLC46A1-39899-ES and IARS-86836-ES AS events may be potential targets for cholangiocarcinoma therapy." (PMID 34055632, 2021). "Additionally, AS events SLC46A1-39899-ES, IARS-86836-ES, and the CDK11A splicing factor may be therapeutic targets for cholangiocarcinoma." (PMID 34055632, 2021).
dementia (1 paper, 2024). Loss of intellectual abilities interfering with an individual's social and occupational functions. "The genes with much more significant association with clinical dementia, but not with AD diagnoses, include SLC46A1 and LFNG." (PMID 38343831, 2024).
glioblastoma (1 paper, 2019). The most malignant astrocytic tumor (WHO grade IV). "The gain of copy number variations (CNV) for PCFT (SLC46A1), compared to the normal brain tissue, was detected in 25% of glioblastoma cases, with CNV loss in 68.75% (data obtained from 16 cases)." (PMID 31003476, 2019). "Nine human glioblastoma specimens were investigated in order to evaluate the level of gene expression of PCFT (SLC46A1) and FOLR1." (PMID 31003476, 2019).
tumor (16 papers, 2018 to 2026). "Clinically, we found a significant inverse correlation between SLC46A1 expression and folate levels in tumor interstitial fluids of CRC, suggesting impaired folate uptake in low SLC46A1 tumors." (PMID 41620398, 2026). "The graphical abstract illustrates the differential impact of SLC46A1 on folate metabolism and gene expression in normal versus tumor cells, highlighting its potential as a therapeutic target in CRC." (PMID 41620398, 2026). "Functional studies demonstrated that SLC46A1-mediated folate uptake suppressed tumor proliferation, migration, and invasion both in vitro and in vivo." (PMID 41620398, 2026). "There was a negative correlation between 5-MTHF concentration in plasma of untreated patients and expression of GGH and SLC46A1/PCFT in tumour." (PMID 30269276, 2018). "The results of the study showed that tumour tissue of untreated patients had higher expression of FPGS, GGH, MTHFD1L, and SLC19A1/RFC-1 compared with mucosa, whereas expression of ABCC3/MRP3 and SLC46A1/PCFT was higher in mucosa compared with tumour." (PMID 30269276, 2018). "This study elucidates the tumor-suppressive role of the folate transporter SLC46A1 in CRC." (PMID 41620398, 2026). "After leaking from tumor blood vessels due to the disruption of the blood brain barrier (BBB), the conjugate is taken up by tumor cells, mediated by SLC46A1, a heme carrier protein 1, and other factors, and accumulates into the tumor cells due to the enhanced permeability and retention (EPR) effect." (PMID 30949484, 2019). "In CRC, however, SLC46A1 downregulation induces intracellular folate deficiency, triggering locus-specific DNA hypomethylation at the FOS promoter, which activates oncogenic transcription of key downstream effectors (CCND1, BCL2, PLAU), driving tumor progression." (PMID 41620398, 2026). "Here, we report that the folate exerts a tumor-suppressive role in CRC; however, the manifestation of this effect is restricted by the expression level of folate transporter SLC46A1 in CRC cells." (PMID 41620398, 2026). "However, this was not the case for ABCC3/MRP3 and SLC46A1/PCFT, which consistently had higher expression levels in mucosa, compared to tumour in each of the treatment groups." (PMID 30269276, 2018). "However, this was not the case for ABCC3/MRP3 and SLC46A1/PCFTPCFT, which had higher expression levels in mucosa compared to tumour." (PMID 30269276, 2018).
cancer (15 papers, 2017 to 2024). A tumor composed of atypical neoplastic, often pleomorphic cells that invade other tissues. "In contrast, in cancer cells, folic acid is preferentially taken up by a folate receptor (FR) which has a high affinity, but a low capacity, while intestinal uptake is predominantly mediated by the proton-coupled folate transporter (PCFT/SLC46A1)." (PMID 39234107, 2024). "SLC46A1 and FRs are often specifically expressed or upregulated in cancer cells." (PMID 36575193, 2022).
genetic diseases (1 paper, 2022). "Some rare genetic diseases are also etiologically linked to CFD, such as hereditary folate malabsorption due to SLC46A1 (also called PCFT or HCP." (PMID 36671766, 2022).
SLC46A1 also shares sentences with these, for which no sentence is quoted: anaemia (2 papers); Cerebral folate deficiency (2); gastric cancer (2); malignant mesothelioma (2); mesothelioma (2); neurological disorder (2); alcohol abuse (1); glioma (1); lung carcinoma (1); macrocytic anaemia (1); metabolic disorder (1); neural tube defect (1); non-small cell lung carcinoma (1); Pancytopenia (1); polycystic kidney (1); rheumatoid arthritis (1).